IGF2BP3 (insulin like growth factor 2 mRNA binding protein 3)
Diseases named in the same sentence as IGF2BP3 in open-access papers (continued):
Sharing a sentence is not in itself a finding about the gene and the disease.
nasopharyngeal carcinoma (11 papers, 2022 to 2025). A carcinoma arising from the nasopharyngeal epithelium. "An in vitro study of nasopharyngeal carcinoma showed that IGF2BP3 regulates key EMT regulatory factors by activating the AKT/mTOR signalling pathway, thus promoting the migration and invasion of nasopharyngeal carcinoma cells." (PMID 38358034, 2024). "The IGF2BP3–lncRNA TINCR–ACLY–PADI1–MAPK–MMP2/9 axis plays an important role in nasopharyngeal carcinoma progression and chemoresistance." (PMID 37298373, 2023). "IGF2BP3 promotes the migration and invasion of nasopharyngeal carcinoma cells through the AKT/mTOR signaling pathway." (PMID 37298373, 2023). "IGF2BP3, a well-known m6A reader, is deregulated in many cancers, but its role in nasopharyngeal carcinoma (NPC) remains unclear." (PMID 35136045, 2022). "For instance, IGF2BP3, an m6A reader, is highly expressed in both LUSC and nasopharyngeal carcinoma (NPC), with elevated expression correlating positively with poor prognosis." (PMID 40867324, 2025). "IGF2BP3 recognizes and reads m6A sites in KPNA2 mRNA to promote its stability and expression, activating tumor growth and metastasis in nasopharyngeal carcinoma." (PMID 37280679, 2023). "IGF2BP3 promotes the stability and storage of its target gene MYC mRNA in a m6A-dependent manner under normal and stress conditions, thereby affecting gene expression output and promoting the occurrence and development of cancer, such as neuroblastoma and nasopharyngeal carcinoma 33-35." (PMID 38577615, 2024).
triple-negative breast carcinoma (11 papers, 2015 to 2025). An invasive breast carcinoma which is negative for expression of estrogen receptor (ER), progesterone receptor (PR), and human epidermal growth factor receptor 2 (HER2). "Prior studies in triple-negative breast cancer have implicated IGF2BP3 in the genesis and function of cancer stem cells, through direct regulation of SLUG transcripts, which in-turn regulates Sox2." (PMID 37760460, 2023). "In triple-negative breast carcinomas (TNBCs), IGF2BP3 is also associated with tumor aggression and poor outcome by participating in the EGFR-mediated migration process and promotes chemoresistance by stabilizing the mRNA of ABCG2 protein." (PMID 32083017, 2019). "And digestive tumor research can reference its mechanisms elsewhere, e.g., metastasis inhibition via circNAV3/miR-4262/ST6GALNAC5/EGFR (as in triple-negative breast cancer) or progression suppression through m6A/IGF2BP3-stabilized TWIST1 mRNA." (PMID 40978472, 2025). "For example, the aberrant level of IGF2BP3 is detected in the majority of invasive triple-negative breast carcinomas, while the expression of IGF2BP3 is only elevated in adenoid cystic carcinomas in basal-like BC." (PMID 34329193, 2021). "IGF2BP2 and IGF2BP3 synergistically promote the metastasis of triple-negative breast cancer by promoting the inactivation of progesterone receptors." (PMID 33550985, 2021). "In triple-negative breast cancer cells, an IGF2BP3 depletion increased cell sensitivity to doxorubicin and mitoxantrone." (PMID 32010687, 2019). "IGF2BP3 was previously reported to be preferentially expressed in triple-negative breast cancers, which exhibit multi-drug resistance and increased aggressiveness." (PMID 26327240, 2015). "These mediators were identified as IGF2BP3 targets by PAR-CLIP studies and were subsequently validated in triple-negative breast cancer cells; however, the exact mechanisms of IGF2BP3-mediated regulation are still unknown." (PMID 32010687, 2019). "In triple-negative breast cancer cells, EGFR signaling regulates IGF2BP3 transcription since the IGF2BP3 promoter activity decreased after MEK1/2 signaling inhibition downstream of EGFR." (PMID 32010687, 2019). "Further, we reported another mechanism by which IGF2BP3 knockdown reduced the MMP2 and MMP9 protein levels in OCCC, as shown in triple negative breast cancer before." (PMID 32083017, 2019).
laryngeal squamous cell carcinoma (10 papers, 2021 to 2026). A squamous cell carcinoma that arises from the larynx. "RBM15‐mediated m6A modification of BAX inhibitor motif containing 6 (TMBIM6) by recruiting IGF2BP3 to promote the progression of laryngeal squamous cell carcinoma." (PMID 40923717, 2026). "RBM15 has been manifested to mediate m6A modification of transmembrane BAX inhibitor motif containing 6 (TMBIM6) mRNA via depending on the reader protein IGF2BP3 in laryngeal squamous cell carcinoma." (PMID 41272900, 2025). "The m6A modification of TMBIM6 mediated by RBM15 increases its stability in an IGF2BP3-dependent manner, promoting the development and progression of laryngeal squamous cell carcinoma." (PMID 40435202, 2025). "RBM15 regulates the stability of TMBIM6 in an IGF2BP3-dependent manner, promoting the progression of laryngeal squamous cell carcinoma." (PMID 39039611, 2024). "The role of IGF2BP3 modulates laryngeal squamous cell carcinoma progression through TMBIM6 mRNA." (PMID 38355626, 2024). "For example, Overexpression of RBM15 increased laryngeal squamous cell carcinoma cell proliferation, migration, invasion, and apoptosis by regulating TMBIM6 stability in an IGF2BP3-dependent manner." (PMID 38765115, 2024). "In laryngeal carcinoma, RBM15 and IGF2BP3 are involved in m6A methylation modification of TMBIM6, thereby regulating the expression of TMBIM6 in laryngeal squamous cell carcinoma (LSCC)." (PMID 36793593, 2023). "Additionally, RBM15 may interact with Insulin-like growth factor 2 mRNA-binding protein 3 (IGF2BP3) and collaborate in the m6A modification of TMBIM6, consequently promoting the malignant progression of laryngeal squamous cell carcinoma." (PMID 38915367, 2024).
oral squamous cell carcinoma (10 papers, 2021 to 2025). "Baicalin has also been reported to alleviate lactate-induced acidification in tumor microenvironment by decreasing the level of m6A reader IGF2BP3 in oral squamous cell carcinoma cells." (PMID 40771928, 2025). "High circIGHG promotes epithelial–mesenchymal transition through sponging miR‐142‐5p to control IGF2BP3, thereafter increasing the aggressiveness of oral squamous cell carcinoma." (PMID 38159063, 2024). "circFOXK2 cooperates with IGF2BP3 to accelerate aerobic glycolysis in oral squamous cell carcinoma by stabilizing GLUT169." (PMID 37554271, 2023). "For example, IGF2BP3 activity could be elevated by circIGHG, thus promoting metastasis of oral squamous cell carcinoma (OSCC) via epithelial-mesenchymal transition." (PMID 37407973, 2023). "Multivariate analysis showed that IGF2BP3 could be used as an independent predictor of oral squamous cell carcinoma." (PMID 36237306, 2022). "During glucose metabolism, IGF2BP3 can maintain the stability of GLUT1 mRNA, which is related to aerobic glycolysis in oral squamous cell carcinoma." (PMID 37298373, 2023). "It has been reported that circ-IGHG manipulates IGF2BP3 through miR-142-5p in OSCC, thus accelerating the progression of oral squamous cell carcinoma." (PMID 36237306, 2022).
endometrial cancer (9 papers, 2017 to 2025). Primary or metastatic malignant neoplasm involving the endometrium (mucous membrane that lines the endometrial cavity). "To further explore the molecular mechanisms underlying IGF2BP3’s role in UCEC, we analyzed the association between SNPs affecting IGF2BP3 expression and the risk of endometrial cancer." (PMID 39883704, 2025). "For instance, in endometrial carcinoma, IGF2BP3 interacts with lncRNA LINC00958 to stabilize E2F3 mRNA, driving tumor progression." (PMID 40313617, 2025). "Furthermore, E2F3 expression is regulated by IGF2BP3 after generation of IGF2BP3- LINC00958 complex in favor of increasing endometrial cancer cells proliferation and migration." (PMID 38075202, 2024). "Furthermore, IGF2BP3 with L1CAM is the best combination to distinguish low- from high-grade endometrial cancer." (PMID 37298373, 2023). "The results of our study illustrated novel insights into the regulation of endometrial carcinoma progression mediated by lncRNAs and IGF2BP3, which highlighted the value of IGF2BP3 combined with LINC00958 as predictors for prognosis and therapeutic candidates in EC." (PMID 35676262, 2022). "In general, this study revealed that IGF2BP3 could promote the proliferation, migration, and invasion of endometrial carcinoma." (PMID 35676262, 2022). "However, the function of IGF2BP3 in endometrial carcinoma has not been studied." (PMID 35676262, 2022).
esophageal cancer (9 papers, 2019 to 2025). A primary or metastatic malignant neoplasm involving the esophagus. "According to established clinical criteria (AUC > 0.7: moderate diagnostic value; AUC>0.9: high diagnostic utility), IGF2BP3 demonstrated high diagnostic capacity for esophageal cancer, suggesting strong diagnostic value for its detection." (PMID 40765570, 2025). "The diagnostic accuracy of IGF2BP3 is found to be highest for esophageal cancer." (PMID 40765570, 2025). "In esophageal cancer, four genes were positively correlated with IGF2BP3: KLHL7, C7orf30, NUPL2, and RAD51L3." (PMID 40765570, 2025). "In summary, IGF2BP3 plays a tumor-promoting role in esophageal cancer and is related to radiosensitivity and the immune response." (PMID 37298373, 2023). "Given that we conducted a preliminary study on the function of IGF2BP3 as a tumor promoter in esophageal cancer, we aimed to elucidate the expression characteristics and biological functions of IGF2BP3 in NPC." (PMID 35136045, 2022). "IGF2BP3 also appears to be involved in immunity in esophageal cancer." (PMID 37298373, 2023). "Similarly, IGF2BP3 is used for constructing prognostic models of esophageal cancer." (PMID 37298373, 2023). "Therefore, IGF2BP3 may become a powerful marker to inhibit the progression of esophageal cancer." (PMID 37298373, 2023).
neuroblastoma (9 papers, 2013 to 2025). Neuroblastoma (NB) is the most common solid, extracranial childhood tumor. "Neuroblastoma patients with elevated IGF2BP3 expression tend to have undifferentiated histology, advanced stages, and an unfavorable prognosis." (PMID 39342406, 2024). "Makorin ring finger protein (MKRN2) regulates its downstream molecules in an IGF2BP3‐dependent manner in neuroblastoma, indicating the ubiquitination modification of IGF2BP3." (PMID 37877353, 2023). "In agreement, IGF2BP3 was proposed a marker of high clinical significance in neuroblastoma, with IGF2BP3-positive patients having decreased overall survival." (PMID 23069990, 2013). "MKRN2, an E3 ligase, was found to be involved in the ubiquitination of IGF2BP3 in neuroblastoma." (PMID 38565547, 2024). "Moreover, IGF2BP3 expression was observed to be decreased following retinoid acid treatment, and its knock-down resulted in reduced invasion ability of neuroblastoma cells." (PMID 39342406, 2024). "In neuroblastoma, MKRN2 down‐regulated the expression of IGF2BP3‐targeted downstream pathways, indicating a negative regulatory effect of ubiquitination on IGF2BP3 function." (PMID 37877353, 2023).
non-small cell lung carcinoma (9 papers, 2022 to 2025). A group of at least three distinct histological types of lung cancer, including non-small cell squamous cell carcinoma, adenocarcinoma, and large cell carcinoma. "Meanwhile, other researchers have shown that IGF2BP3 inhibits CD8+ T cell responses to facilitate tumor immune evasion by promoting the deubiquitination of PD-L1 in non-small cell lung cancer." (PMID 36686749, 2022). "Additionally, insights from the GSE231938 dataset revealed a positive association between GLS1 and IGF2BP3 in non-small cell lung cancer, prompting further exploration into the interplay among GLS1, IGF2BP3 and UCA1." (PMID 38760723, 2024). "For example, METTL3 promotes the formation of circ-IGF2BP3 in a YTHDC1-dependent manner, protecting PD-L1 from proteasome-mediated degradation, thereby reducing CD8+ T cell infiltration and promoting immune evasion of non-small cell lung cancer (NSCLC) cells." (PMID 39286028, 2024). "In non-small cell lung cancer, lncRNA linc-SPRY3 could bind to IGF2BP3 (Insulin Like Growth Factor 2 MRNA Binding Protein 3), which leads to the destabilization of c-Myc and HMGA2, and improves the radiosensitivity of tumors." (PMID 35600868, 2022).
pancreatic ductal adenocarcinoma (9 papers, 2010 to 2023). An infiltrating adenocarcinoma that arises from the epithelial cells of the pancreas. "IGF-2, in comparison to IGF2BP3, was expressed not only in pancreatic ductal adenocarcinoma, but also in benign pancreatic tissue." (PMID 20178612, 2010). "Our data suggest that IGF2BP3 overexpression identifies a subset of pancreatic ductal adenocarcinomas with an extremely poor outcome and supports the rationale for developing therapies to target the IGF pathway in this cancer." (PMID 20178612, 2010). "We evaluated the expression of IGF2BP3 by immunohistochemistry using a tissue microarray of 127 pancreatic ductal adenocarcinomas with tumor grade 1, 2 and 3 according to WHO criteria, and the prognostic value of IGF2BP3 expression." (PMID 20178612, 2010). "Collectively, these observations led us to postulate that IGF2BP3 expression could be a prognostic indicator for pancreatic ductal adenocarcinoma." (PMID 20178612, 2010). "Although the function of IGF2BP3 in pancreatic ductal adenocarcinoma remains unclear, transgenic overexpression of the protein in mice was reported to induce abnormalities in the exocrine pancreas." (PMID 20178612, 2010). "Western blot results showed that, compared to hTERT-HPNE, model genes including KRT7, KRT19, IGF2BP3, and CXCL5, were significantly increased in human pancreatic ductal carcinoma cell lines, PANC-1 and PL45." (PMID 37371833, 2023). "IGF2BP3 was found to be selectively overexpressed in pancreatic ductal adenocarcinoma tissues but not in benign pancreatic tissues." (PMID 20178612, 2010). "IGF2BP3 is selectively overexpressed in pancreatic ductal adenocarcinoma tissues but not in benign pancreatic tissues, consistent with previous reports." (PMID 20178612, 2010).
lymph node metastasis (7 papers, 2017 to 2025). "In univariate analysis, age, diffuse type, high grade, advanced stage, lymph node metastasis and overexpression of IGF2BP3 had a statistical association with poor survival." (PMID 28399871, 2017). "When the mutation is a THADA/IGF2BP3 fusion, the surgeon might be less inclined to perform this lymph node exploration because they are aware that the likelihood of lymph node metastases is significantly less." (PMID 37444504, 2023). "Moreover, advanced lymph node metastasis was linked to IGF2BP3 expression." (PMID 40801655, 2025). "We found a significant correlation between IGF2BP3 expression and the presence of axillary lymph node metastasis, with lower expression in patients with metastasis." (PMID 40672753, 2025). "Chiao-ying Lin, Shengjin Li, and Ki-Yeol Kim’s team found that IGF2BP3 overexpression in OSCC cells was associated with higher histological grade, lymph node metastasis, advanced tumor, and clinical stage." (PMID 36237306, 2022). "Lymph node metastasis in patients with squamous cell carcinoma is correlated with IGF2BP3 and PDPN expression." (PMID 36237306, 2022). "Moreover, the expression level of IGF2BP3 was significantly related to the N stage and lymph node metastasis, suggesting that IGF2BP3 was intimately related to the malignancy progression and clinical features." (PMID 34446007, 2021).
astrocytoma (6 papers, 2017 to 2023). "According to the gene expression microarray analysis of 9 pilomyxoid astrocytoma (PMA) and 13 pilocytic astrocytoma (PA) from lower and upper loci, the expression level of IGF2BP3 in malignant astrocytoma is significantly increased." (PMID 32943100, 2020). "In a single-cell RNA-seq analysis of astrocytoma dataset, 23 out of 28 m6A-RMRs (82%) (except ALKBH5, IGF2BP1, IGF2BP2, IGF2BP3, and G3BP2) were in the medium to high expression levels in malignant cells of astrocytoma." (PMID 35211628, 2022). "The mRNA and protein expression levels of IGF2BP3 are upregulated in GBM but not significantly upregulated in low-grade astrocytomas." (PMID 32943100, 2020).
laryngeal carcinoma (6 papers, 2021 to 2024). Carcinoma that arises from the laryngeal epithelium. "IGF2BP3 indirectly promotes the invasion and migration of laryngeal cancer in the process of IGF2BP3-dependent methylation modification." (PMID 36237306, 2022). "In previous literature reports, immunohistochemical analysis found that the expression of IGF2BP3 was higher in laryngeal cancer tissues than in tissue adjacent to carcinoma." (PMID 36237306, 2022). "There are few studies on IGF2BP3 in laryngeal cancer, but the existing literature has shown that IGF2BP3 expression is elevated in laryngeal cancer tissue, suggesting that IGF2BP3 plays an important role in the occurrence and development of laryngeal cancer." (PMID 36237306, 2022). "All these results support the hypothesis that IGF2BP3 can be used as a new biomarker in the diagnosis of laryngeal cancer." (PMID 36237306, 2022). "In addition, our research also identified the expression of IGF2BP3 in laryngeal cancer." (PMID 33637103, 2021). "The expression of IGF2BP3 in laryngeal cancer tissues was significantly higher than that of noncancerous tissues adjacent to cancer and was associated with a poor prognosis." (PMID 33637103, 2021). "Additionally, IGF2BP3-mediated m6A modification could promote the stabilization of TMA7 mRNA, thereby contributing to cancer progression and DDP resistance in laryngeal cancer." (PMID 39731162, 2024).
lymphoma (6 papers, 2013 to 2026). A malignant (clonal) proliferation of B- lymphocytes or T- lymphocytes which involves the lymph nodes, bone marrow and/or extranodal sites. "In conclusion, miR-486 inhibits the proliferation of lymphoma cells and tumorigenesis induced by radiation through targeting IGF2BP3." (PMID 33692937, 2020). "IGF2BP1 and IGF2BP3 are re-expressed in several aggressive cancers in colorectal and lymphomas with a high incidence of more than 70%." (PMID 28693523, 2017). "In addition, IGF2BP3 expression is correlated with the aggressiveness or proliferative phenotypes of lymphoma." (PMID 32293476, 2020). "As a result, miR-486 could inhibit proliferation of mouse lymphoma cells by targeting IGF2BP3 mRNA." (PMID 33692937, 2020). "Previous research has illustrated that IGF2BP3 (IMP-3) overexpression is seemingly restricted to several epithelial malignancies correlated with aggressive behavior and lymphomas originating from physiologic germinal center B cells." (PMID 34802044, 2022). "In contrast to peripheral lymphoid tissue and lymphomas, IGF2BP3 expression has not been studied previously in precursor B cells from normal pediatric BM, and its physiological role in this tissue remains mainly unknown." (PMID 23936243, 2013).